STK11 (serine/threonine kinase 11)
Diseases named in the same sentence as STK11 in open-access papers (continued):
Sharing a sentence is not in itself a finding about the gene and the disease.
tumor (continued). "In summary, our work supports the use of tumor STK11/LKB1 loss of function as a CC biomarker with predictive and prognostic value." (PMID 37092555, 2023). "CC wasting in mice with STK11/LKB1-variant tumors was associated with significant alterations in tumor microenvironment immune cell repertoire, concomitant amplification of local and systemic pro-inflammatory cytokines, and host adipose STAT3 activation." (PMID 37092555, 2023). "In summary, understanding how STK11 mutation influences tumor immunity is crucial to the development of effective individualized treatments for LUAD." (PMID 37506141, 2023). "Overall, our work proposes variants in tumor STK11/LKB1 as predictive/prognostic biomarkers for CC that also have a parallel biologic role in the syndrome’s development." (PMID 37092555, 2023). "Loss of function in the STK11 or LKB1 tumor suppressor genes, as well as CD44-IGF1R fusion, or the up-regulation of NOS3 and ARHGAP4 also leads to LP, increases nodal involvement and promotes epithelial mesenchymal transition through the MAPK pathway." (PMID 37834127, 2023). "Mutational analysis of circulating tumor DNA from patients with NSCLC identified 89% concordance between STK11/LKB1 mutations and weight loss at cancer diagnosis." (PMID 37092555, 2023). "Through repression of the NOX1/VEGF axis and activation of mTOR and HIF1-α, STK11 loss triggers tumor vascularization." (PMID 37370686, 2023). "Of the seven patients with major pathological response (≤10% viable tumor cells), one had mutations in STK11 and had disease progression." (PMID 36672698, 2023). "The authors also reported that in patients with NSCLC who underwent comprehensive tumor genome profiling, STK11 and ATM mutations were significantly enriched in tumors harboring G12C, G12A and G12V." (PMID 36348317, 2022). "Tumor testing revealed clinically relevant molecular alterations, including the known germline pathogenic variant STK11, a KRAS somatic pathogenic variant, and FGFR3 gene amplification." (PMID 35543335, 2022). "These genes all have different functions and effects: KRAS is a tumor-specific mutation that promotes the initiation and progression of cancers, and STK11 is a tumor suppressor that loses function after mutations." (PMID 35159000, 2022). "STK11 acts as a tumor suppressor in cancer because loss of function promotes proliferation and tumorigenesis." (PMID 35904643, 2022). "In our study, all three patients with mutations in STK11 demonstrated tumor shrinkage and had a missense mutation at amino acid 354, leading to conversion of the wild-type residue phenylalanine to a leucine (STK11, p.F354L, c.1062C > G)." (PMID 35904643, 2022). "STK11 is a tumor suppressor encoding for the serine/threonine kinase STK11, also known as liver kinase B1 (LKB1), and it regulates cell polarity and energy metabolism." (PMID 36077640, 2022). "PJS is caused by germline mutations in serine-threonine kinase 11 (STK11), a tumor suppressor gene localized on chromosome 19p13.3." (PMID 36033506, 2022). "As a tumor suppressor gene, STK11 located on chromosome 19p 13.3, and variants of STK11 were confirmed as the key determinants of PJS." (PMID 36550395, 2022). "In more than two-thirds of cases, the mutated STK11 (19p13.3) gene is the main culprit, which is a tumor-suppresser gene, that encodes for the Serine/Threonine Kinase 11 (Liver Kinase B1)." (PMID 36421339, 2022). "Increased mTOR signaling is particularly related to human malignancies defined by the loss or mutation of critical tumor suppressors including STK11, TSC1/2, and PTEN which seem to be important for regulating the PI3K/Akt pathway." (PMID 36109789, 2022). "In KRAS-driven NSCLC, inactivation of tumor-suppressor gene STK11/LKB1 was associated with downregulation of PD-L1 and suppressed effector T-cells." (PMID 35884355, 2022).
tumor (continued). "Serine/threonine kinase 11 (Stk11), which encodes liver kinase b1 (Lkb1), is a tumor suppressor that links energy metabolism with cell growth and proliferation." (PMID 35115536, 2022). "Along with high KRAS mutation rates and RAS84 expression, RAG-1 was characterised by STK11/LKB1 mutations (KL tumours) and RAG-4 by CDKN2A mutations (KC tumours)." (PMID 36163168, 2022). "Next-generation sequencing (NGS) revealed other than STK11 germline mutation, the tumor also harbors GNAS somatic mutation at codon 478 and EGFR amplification." (PMID 36578081, 2022). "This also reflected statistically lower time to progression (TTP) in patients having both mutations in KRAS and STK11 genes compared to the tumor with only KRAS mutations." (PMID 34164344, 2021). "Here we demonstrate the functional impact of STK11 splice-site variants can be established by simply sequencing RT-PCR amplicons from tumor mRNA." (PMID 34849607, 2021). "Inactivation of STK11 has been shown to cause a “cold” tumor immune microenvironment by blunting the action of cytotoxic T lymphocytes and has been associated with PD‐1/PD‐L1 inhibitor resistance in NSCLC." (PMID 33314633, 2021). "According to publicly available tumor sequencing databases, ~1–3% of all somatic STK11 single nucleotide variants in NSCLC occur at predicted splice-sites." (PMID 34849607, 2021). "The advanced tumor progression with loss of Stk11 resulted in a metastasis in the abdomen of one mouse." (PMID 33652656, 2021). "For tumor suppressor genes like STK11, interpreting nonsense variants occurring early in the coding region is trivial." (PMID 34849607, 2021). "Recently, a STK11/LKB1 co‐mutation in KRAS‐mutant NSCLC was reported as a new predictive marker for tumor resistance to ICI therapy." (PMID 33655698, 2021). "STK11 gene and the serine threonine kinase encoded by it are tumor suppressors, which regulate cell metabolism and growth through phosphorylation of adenosine monophosphate activated protein kinase (AMPK) and 12 AMPK-related kinases." (PMID 33633793, 2021). "Loss of Stk11/Lkbn1 impacts tumor cell metabolism and increases ROS production, while elevated abundance of Nrf2 establishes ROS homeostasis, enabling tumor cells to grow under stress conditions." (PMID 33738287, 2021). "Inactivating LKB1/STK11 mutations generally cause poor response to anti-PD-1 monoclonal antibodies, even if they correlate with an elevated tumor mutational burden (TMB) and an increased number of neoantigens." (PMID 34944952, 2021). "The discovery that STK11 (encoding LKB1) haploinsufficiency promoted tumors initially suggested that AMPK was a tumor suppressor." (PMID 34885077, 2021). "Loss of Stk11 results in rapid tumor development where mice reach human endpoint four months after initiation." (PMID 33652656, 2021). "While these data are exploratory, it is known that STK11-mutated tumours have a poor response to immunotherapy and KRYSTAL-1 data open the possibility of a biomarker-driven effect in this difficult-to-treat subgroup." (PMID 34200676, 2021). "Serine/threonine kinase 11 (STK11) encodes liver kinase B1 (LKB1) and is a commonly altered tumor suppressor that frequently occurs in NSCLC." (PMID 33968782, 2021).
tumor (continued). "STK11 appears to be inactivated or mutated in sporadic cancers whose spectrum of tumor types suggests cooperation with exposure to environmental carcinogens." (PMID 32647375, 2020). "Consistent with LKB1 being a tumour suppressor, many human cancer cell lines carry loss-of-function mutations in the STK11 gene that encodes it." (PMID 33375416, 2020). "Some studies have linked the proximity of the SMARCA4 locus to the STK11 locus (another well-known LUAD tumor suppressor gene) and the loss of heterozygosity that recurrently affects the short arm of the chromosome 19 in LUAD." (PMID 33321963, 2020). "Further studies on the association of STK11 mutations in response to ICB are warranted since other mutations in the tumour will also influence the clinical response." (PMID 33015859, 2020). "STK11 (or LKB1) is a tumor suppressor gene and its loss of function is associated with tumor metastasis in lung and head–neck cancers." (PMID 33149122, 2020). "LUAD patients harboring STK11 mutations were shown to have low densities of CD8+ TILs in tumor beds, in contrast to STK11 wildtype LUAD patients who displayed high levels of CD4+ and CD8+ T cells." (PMID 32117295, 2020). "Mechanistically, inactivating mutations in the tumor suppressor STK11 were able to reprogram the TME into so-called “immune-deserts,” which support a “cold” tumor." (PMID 32117295, 2020). "It meant that LUAD harboring STK11 mutations can cause the “cold” tumor immune microenvironment, which is owing to the low expression of STK11 genes." (PMID 33425731, 2020). "STK11 encodes the protein Serine/Threonine Kinase 11, a tumor suppressor; mutations in this gene have been associated with Peutz–Jeghers syndrome." (PMID 32580435, 2020). "Then, we investigated the association between the clusters and clinical characteristics, and sex, tumor stage, smoking history, STK11 mutation, and KEAP1 mutation were significantly (P‐value < 0.05) associated with clusters." (PMID 32688456, 2020). "In agreement with our data, RB1 mutations occurs in 35% of LCNECs as well as typical NSCLC mutations such as KEAP1 and STK11 only occur in this tumor variants compared to both NETs and SCLCs (p < 0.0001)." (PMID 32987854, 2020). "Loss of Stk11/Lkb1 in KPL mice dramatically increased tumour area and shortened overall survival compared to that of KP mice (Fig EV3D and E)." (PMID 32128997, 2020). "LKB1, which is encoded by STK11, is a serine-threonine kinase that is known best as having tumour suppressive-like activity in cancers." (PMID 32429240, 2020). "The liver kinase B1 (LKB1, also known as STK11) is a serine/threonine kinase that has been found mutated and deregulated in several types of cancers, where it acts as a tumor suppressor." (PMID 30934935, 2019). "A genetic mutation was identified in two samples: an APC gene mutation and an STK11 mutation, the location of which corresponded to the tumour sample mutations seen in these patients." (PMID 30774772, 2019). "In the tumour suppressor serine/threonine‐protein kinase STK11, pathogenic and VUS identified in Peutz–Jeghers syndrome patients can be similarly linked." (PMID 30573687, 2018). "Other significant somatic mutations were detected on Chromosome 16; BRAF gene (42% tumors), Chromosome 13; KDR (83% tumors) and Chromosome 20; STK11 with one missense variant detected in 8 of 12 (67%) samples in the matched normal and tumor pairs." (PMID 29854308, 2018).
tumor (continued). "While KRAS is a common oncogene in lung ADC, LKB1/STK11, encoding a serine-threonine kinase implicated in energy sensing and cell polarity, is notable as being among the most commonly mutated tumour suppressors in ADC2." (PMID 28387316, 2017). "LKB1, a tumor suppressor, is also known as serine/threonine kinase 11 (STK11), with germline mutations in LKB1/SKT11 causing the Peutz-Jeghers tumor predisposition syndrome." (PMID 26779371, 2015). "Patients with TSC1, TSC2 or LKB1 (STK11) tumour mutations will be eligible for treatment with AZD2014." (PMID 26410619, 2015). "Somatic mutations in genes encoding AMPK appear to be less frequent in tumours than those in STK11, perhaps due to redundancy between multiple AMPK isoforms." (PMID 24467442, 2014). "We found variants in the five genes APC, BRCA1, RET, RNASEL, and STK11 that were linked to autosomal dominant forms of cancer or neoplasm as well as four complex risk variants in ELAC2, MSR1, AIP, and SDHB." (PMID 25333069, 2014). "LKB1/STK11 is mutated in sporadic human cancers whose spectrum of tumor types suggests cooperation with exposure to environmental carcinogens." (PMID 25329316, 2014). "LKB1 is a well-established tumor suppressor, with both germline and somatic mutations in STK11, the gene encoding LKB1, associated with cancer development." (PMID 24280377, 2013). "Based on preclinical testing, mtor inhibitors were predicted to be effective in the treatment of tumours with genetic mutations that lead to overactivation of mtor signalling—for example, loss of pten, Stk11 (Lkb1), or Tsc2." (PMID 19229373, 2009). "Beyond cell-autonomous resistance mechanisms, the STK11 mutation-driven immunosuppressive tumor microenvironment (TME) may also compromise the efficacy of G12Ci." (PMID 41541668, 2026). "Tumor-intrinsic-resistant mechanisms involve low tumor mutational burden, compromised antigen presentation machinery, alterations in the interferon-gamma pathway, and loss of tumor suppressors such as STK11/LKB1." (PMID 40718320, 2025). "However, the mechanism by which KEAP1 or STK11 mutations impeding tumor immunogenicity and immunotherapeutic response remains elusive." (PMID 41378285, 2025). "STK11 variants can also modulate the tumor immune microenvironment." (PMID 40860288, 2025). "The higher frequency of KEAP1/STK11 co-mutations in patient-derived cell lines compared with tumor datasets suggests a potential selective advantage for in vitro establishment, possibly because of enhanced glutamine utilization and reactive oxidative stress resistance." (PMID 40427178, 2025). "Additionally, in KRAS mutant LUAD, the tumor suppressors LKB1/STK11 and KEAP1 are frequently mutated, both of which have been shown to drive immune evasion." (PMID 40849659, 2025). "At this point, lower PD-L1 expression can be indirectly linked to STK11 mutation due to lower T-cell activity and smaller amount of IFNγ secreted by these cells, which is known as a cytokine, inducing PD-L1 expression in STK11 mutated tumours." (PMID 40650126, 2025). "Moreover, somatic missense mutation in STK11 in human cancers impairs its tumor-suppressive function and promotes cell motility independently of its kinase activity." (PMID 41051525, 2025). "Other studies confirmed beforementioned results regarding STK11/LKB1 co-mutations, suggesting that LKB1-deficient tumor cells stimulate neutrophil recruitment through the production of cytokines and chemokines and changes in metabolic reprogramming, which lead to a worse prognosis in such patients." (PMID 40558308, 2025).
tumor (continued). "STK11 mutations are present in variable percentages in different tumor types." (PMID 40591555, 2025). "Thus, tumours harbouring STK11 mutations can be classified as immunologically “cold” and predictive of a lack of clinical benefit from immune checkpoint inhibitors." (PMID 40647497, 2025). "Additionally, STK11 mutations were again found exclusively in SD tumours among S-LUAD, mirroring the pattern observed in NS-LUAD." (PMID 41509216, 2025). "Importantly, PEBP1/STK11 co-expression was consistently linked to reduced expression of drug resistance genes and greater chemosensitivity across multiple tumor types." (PMID 40806276, 2025). "Notably, 57 of 58 (98%) of STK11 mutant tumours also feature the LOH on 19p, implying that bi-allelic loss of STK11 is a strong early driving mechanism in SD tumours." (PMID 41509216, 2025). "Interestingly, RunLengthNonUniformity was relatively low in STK11-mutated lesions, possibly reflecting a more diffusely disorganized but texturally consistent tumor pattern." (PMID 41203783, 2025). "Hence, our findings also warrant careful laboratory exploration to more conclusively link KRAS/STK11 mutations, lipid metabolism, and tumor immunity." (PMID 39113608, 2024). "In addition, a truncating mutation of serine/threonine kinase 11 (STK11) promotes tumor progression, and low expression of the STK11 protein is correlated with poor prognosis, mostly in papillary CCA." (PMID 39335604, 2024). "The limitations of our study include its retrospective nature, which resulted in missing data that have been previously associated with PFS, such as corrected tumor mutational burden, combinations of STK11, KEAP, and EGFR mutations, human leukocyte antigens, or tertiary lymphoid structure." (PMID 39001553, 2024). "The underlying mechanism has been linked to the STK11 genetic alteration, resulting in an indolent, immunosuppressive tumour milieu, characterised by lower infiltration of TILs, reduced expression of inflammatory cytokines, and epigenetic inhibition of the stimulator of IFN genes (STING)." (PMID 39749035, 2024). "However, instead of focusing on the tumor-extrinsic processes, we chose to investigate which signaling pathways downstream of STK11 loss drive these tumor-intrinsic transcriptional changes." (PMID 37968341, 2024). "Our results suggested that IRGs might be one of the reasons why STK11 causes changes in the tumor microenvironment." (PMID 38736875, 2024). "STK11 gene alterations are identified in 99% of tumours, including mutations and deletions." (PMID 38376618, 2024). "Fourth, we have preliminarily explored the possible mechanisms of IRGs in STK11 mutations through gene difference analysis and gene function enrichment analysis, but further research is still needed to reveal the mechanisms of tumor microenvironment changes caused by STK11 mutations." (PMID 38736875, 2024). "This may be related to the fact that STK11 deficiency leads to T cell suppression, resulting in reduced numbers of tumour-infiltrating lymphocyte and decreased expression of PD-L1 in tumours." (PMID 39530091, 2024). "Tumor pathogenesis includes STK11, APC, and MDB4 mutations as well as KMT2D variants, which are of unknown biological significance." (PMID 40034930, 2024). "Loss of STK11 significantly increased the tumor volume and weight." (PMID 38461159, 2024). "In addition, KEAP1 and STK11 LOF mutations have both been linked to immune evasion by reducing the number of tumour-infiltrating lymphocytes (TILs) within the TME." (PMID 36864508, 2023). "Consequently, STK11 deficiency triggers the opposite effect, characterized by reduced tumor infiltrating lymphocytes (TILs) and decreased tumor PD-L1 expression." (PMID 37370686, 2023). "Notably, we identified one Chinese EC patient with a deleterious germline variant in the STK11 gene, a known tumor suppressor gene associated with the AMPK and mTOR pathway." (PMID 37730563, 2023).